CLEC2D (C-type lectin domain family 2 member D)
Description:
Receptor for KLRB1 that protects target cells against natural killer cell-mediated lysis. Inhibits osteoclast formation. Inhibits bone resorption. Modulates the release of interferon-gamma. Binds high molecular weight sulfated glycosaminoglycans.
Synonyms: CLAX; LLT1; OCIL
Tractability: Antibody: UniProt places it where antibodies can reach, with high confidence; its Gene Ontology location is reachable by antibodies, with high confidence; UniProt predicts a signal peptide or a membrane-spanning region.
Gene: Protein-coding gene on chromosome 12 (9,664,969 to 9,699,553, forward strand). Ensembl gene ENSG00000069493.
Subcellular location: Cell membrane; Endoplasmic reticulum (Isoform 2); Endoplasmic reticulum (Isoform 4)
Subcellular location (Human Protein Atlas): Golgi apparatus
Pathways (Reactome):
Immune System: Immunoregulatory interactions between a Lymphoid and a non-Lymphoid cell
Gene Ontology:
Molecular function: natural killer cell lectin-like receptor binding; receptor ligand activity; transmembrane signaling receptor activity
Biological process: cell surface receptor signaling pathway; NK T cell activation; T cell receptor signaling pathway
Cellular component: cell surface; endoplasmic reticulum; plasma membrane; external side of plasma membrane; membrane
Genetic constraint (gnomAD): Loss-of-function variants: 7 observed, 8.65 expected, observed/expected ratio (o/e) 0.81, 90% interval 0.46 to 1.5. That is too few expected variants to judge how well the gene tolerates losing a copy. Missense variants: 74 observed, 94.68 expected, observed/expected ratio (o/e) 0.78, 90% interval 0.65 to 0.95. Synonymous variants: 32 observed, 32.59 expected, observed/expected ratio (o/e) 0.98, 90% interval 0.74 to 1.32.
Homologues: Orthologues: macaque CLEC2D (93% identical), chimpanzee CLEC2D (82% identical), dog CLEC2D (64% identical), rat Clec2h (39% identical), mouse Clec2h (38% identical), rat Clec2e (38% identical), mouse Clec2g (37% identical), mouse Clec2e (36% identical), mouse Clec2d (36% identical), mouse Clec2i (34% identical), rat Clec2d2l1 (34% identical), rat Clec2d2l2 (34% identical), and 9 more. Paralogues in human: CLEC2A (33% identical), CLEC2B (32% identical), CD69 (29% identical), CLEC2L (24% identical), KLRF2 (23% identical), KLRC1 (23% identical), KLRG1 (23% identical), KLRB1 (21% identical), KLRG2 (21% identical), OLR1 (21% identical), CLEC9A (21% identical), KLRC2 (20% identical), and 11 more.